MTR (5-methyltetrahydrofolate-homocysteine methyltransferase)
Diseases named in the same sentence as MTR in open-access papers (continued):
Sharing a sentence is not in itself a finding about the gene and the disease.
preeclampsia (4 papers, 2022 to 2026). Preeclampsia is a hypertensive disorder of pregnancy that is characterized by new-onset hypertension with proteinuria presenting after 20 weeks of gestation, and depending on mild or severe forms may initially present with severe headache, visual disturbances, and hyperreflexia. "In contrast, the MTR 2756A > G (A/G) genotype was associated with an increased risk of preeclampsia." (PMID 41595733, 2026). "The rarest type of polymorphism was the MTR A2756G mutation, with 88 cases (4.1%) confirmed among all patients with preeclampsia tested for an MTR polymorphism (N = 2140)." (PMID 39336076, 2024). "The role of the MTR A2756G polymorphism in the development of preeclampsia needs to be further investigated." (PMID 39336076, 2024). "Nevertheless, the polymorphism of MTR at rs1805087 were identified to be significantly associated with the higher risk of other diseases, such as preeclampsia and breast cancer." (PMID 37296303, 2023). "However, the MTR A2756G gene polymorphism was rarely seen in this report among women with preeclampsia." (PMID 39336076, 2024). "Low levels of folate and high levels of homocysteine are found among women with preeclampsia; thus, this fact proves an essential fore of MTR, MTRR, and MTHFR enzymes in coagulation homeostasis and pregnancy maintenance." (PMID 39336076, 2024). "In this study, the highest prevalence of MTR A2756G, MTRR A66G, and MTHFR C677T polymorphism were registered among women with preeclampsia in the 30–34 and 35–39 age groups." (PMID 39336076, 2024). "The researchers explain that the overexpression of MTR in the placenta of women with preeclampsia results in a “potential compensation mechanism” of folate metabolism in preeclampsia." (PMID 39336076, 2024). "This study aimed to evaluate the prevalence of methionine synthase (MTR), methionine synthase reductase (MTRR), and methylenetetrahydrofolate reductase (MTHFR) genes’ polymorphisms among ethnic Kazakh women with preeclampsia." (PMID 39336076, 2024). "The study from Chile also reported overexpression of MTR among women with preeclampsia, contrary to our findings." (PMID 39336076, 2024). "Thus, the study’s aim was to evaluate the prevalence of methionine synthase (MTR), methionine synthase reductase (MTRR), and methylenetetrahydrofolate reductase (MTHFR) genes’ polymorphisms among ethnic Kazakh women with preeclampsia." (PMID 39336076, 2024). "Moreover, multiple studies found that genetic polymorphisms, particularly MTR A2756G, MTRR A66Gm, and MTHFR C677T, are associated with preeclampsia and severe preeclampsia." (PMID 39336076, 2024). "In the context of this genetic study on folate metabolism genes’ polymorphisms (MTR, MTRR, and MTHFR) among ethnic Kazakh women with preeclampsia, an HWE test would evaluate whether the observed genotype frequencies match the expected frequencies based on the genetic principles." (PMID 39336076, 2024). "However, the role of the MTR gene polymorphism in the pathogenesis of preeclampsia is not clearly determined." (PMID 39336076, 2024). "MTRR A66G and MTR A2756G have been proved to be associated with increased homocysteine levels, and a certain concentration of homocysteine could cause endothelial cell dysfunction and oxidative stress, which is positively related to PTB, LBW, and preeclampsia." (PMID 35631247, 2022). "Although this study did not confirm the role of MTR A2756G in the development of preeclampsia, the high prevalence of MTRR A66G and MTHFR C677T polymorphisms were found among women aged 30–39 years old." (PMID 39336076, 2024).
colorectal cancer (3 papers, 2013 to 2024). A primary or metastatic malignant neoplasm that affects the colon or rectum. "Our observation of an interaction between MTR A2756G and alcohol consumption suggests that the DNA methylation pathway is implicated in the development of colorectal cancer." (PMID 23593229, 2013). "Methionine synthase (MTR), which plays a central role in maintaining adequate intracellular folate, methionine and normal homocysteine concentrations, was thought to be involved in the development of colorectal cancer (CRC) and colorectal adenoma (CRA) by affecting DNA methylation." (PMID 23593229, 2013).
liver cancer (3 papers, 2014 to 2023). An epithelial or non-epithelial malignant neoplasm that arises from the liver. "Forty-seven primary liver cancer patients were genotyped for ten polymorphisms: DHFR 19bp ins/del, TS 2rpt-3rpt, MTHFD1 1958G>A, MTHFR 677C>T, MTR 2756A>G, MTRR 66A>G, RFC1 80G>A, SHMT1 1420C>T, BHMT 716 A>G, TC II 776C>G." (PMID 27936032, 2016).
lung carcinoma (3 papers, 2007 to 2019). "In this study, we aimed to evaluate the association of serum folate concentration and of six known functional variations in MTHFR, MTR, MTRR genes and the risk of lung cancer in Poland." (PMID 28493936, 2017). "The analysis of variations in MTHFR, MTR and MTRR genes did not reveal any significant difference between lung cancer cases and controls in univariable and multivariable analyses." (PMID 28493936, 2017). "The distribution of the genotypes in six tested SNPs in MTHFR (rs1801131, rs1801133), MTR (rs1805087) and MTRR (rs1801394, rs1532268, rs10380) genes was not significantly different between lung cancer patients and healthy controls." (PMID 28493936, 2017).
male infertility (3 papers, 2015 to 2025). The inability of the male to effect fertilization of an ovum after a specified period of unprotected intercourse. "In support of the broader relevance of these folate-pathway genes, a recent meta-analysis reported a significant association between the MTR A2756G polymorphism and male infertility." (PMID 41150742, 2025). "Furthermore, the MTR A2756G and MTRR A66G mutations were potentially linked with a risk of male infertility." (PMID 26549413, 2015). "Therefore, it can be speculated that mutations in MTHFR, MTR and MTRR could be possible candidates for male infertility because of the vital functions of folate-related enzymes." (PMID 26549413, 2015). "MTR A2756G and MTRR A66G were potential candidates in the pathogenesis of male infertility, but more case-control studies were required to avoid false-positive outcomes." (PMID 26549413, 2015).
melanoma (3 papers, 2022 to 2024). A malignant, usually aggressive tumor composed of atypical, neoplastic melanocytes. "Taken together, our data indicated that MTR loss combined with MTHFD2 upregulation led to one-carbon unit enrichment and contributed to PRKDC-MXD3/S57-induced melanoma tumor growth." (PMID 39039072, 2024).
thrombophilia (3 papers, 2024 to 2026). A condition characterized by an abnormally high level of thrombi. "This study found that genotypes of seven thrombophilia genes, including MTHFR, SERPINE1, MTR, ANXA5, MTRR PROZ, and VEGFA, are associated with inherited thrombophilia risk for RPL-RIF." (PMID 39498089, 2024).
acute lymphoblastic leukemia (2 papers, 2019 to 2025). Leukemia with an acute onset, characterized by the presence of lymphoblasts in the bone marrow and the peripheral blood. "Plenty of studies have investigated the effect of methionine synthase (MTR) A2756G polymorphism on risk of developing pediatric acute lymphoblastic leukemia (ALL), but the available results were inconsistent." (PMID 30559146, 2019).
atherosclerosis (2 papers, 2022 to 2023). A disease characterized by the build-up of fatty material and calcium deposition in the arterial wall resulting in partial or complete occlusion of the arterial lumen. "The polymorphism of the MTR rs1805087 gene (AG and GG genotypes), resulting in a decrease in the activity of the enzyme methionine synthase, is associated with the development of atherosclerosis." (PMID 35207533, 2022).
colorectal adenoma (2 papers, 2013 to 2021). An adenoma that arises from the colon or rectum. "Furthermore, a functional polymorphism of methionine synthase (MTR) appears to augment the colorectal adenoma potential of alcohol." (PMID 34503214, 2021).
coronary artery disease (2 papers, 2017 to 2020). "Among them, the 5–10-Methylene tetrahydrofolate reductase (MTHFR) and the Methionine synthase (MTR), both regulating homocysteine metabolism, an atherogenic and prothrombotic protein, have been related with an increased risk of coronary artery disease (CAD)." (PMID 33228237, 2020).
Hearing impairment (2 papers, 2011 to 2014). A decreased magnitude of the sensory perception of sound. "In the present analysis, the MTHFR 677 T allele decreased the risk of hearing impairment among the middle-aged and elderly, provided that the MTR A2756G genotype was AA." (PMID 21385350, 2011). "In this study, we investigated whether the MTHFR C677T (rs1801133) and MTR A2756G (rs1805087) polymorphisms are associated with hearing impairment in middle-aged and elderly people in a Japanese community." (PMID 21385350, 2011). "The aim of this study is to investigate the effects of the methionine synthase (MTR) A2756G and methylenetetrahydrofolate reductase (MTHFR) C677T gene polymorphisms on the risk of hearing impairment in middle-aged and elderly Japanese." (PMID 21385350, 2011).
leukemia (2 papers, 2019 to 2022). A malignant (clonal) hematologic disorder, involving hematopoietic stem cells and characterized by the presence of primitive or atypical myeloid or lymphoid cells in the bone marrow and the blood. "Therefore, MTR A2756G polymorphism might lead to alterations in DNA biosynthesis and methylation pattern, and contribute to the genetic susceptibility to cancer including leukemia, as hypermethylation is important in acute leukemia." (PMID 30559146, 2019). "Simultaneous MMA and leukemia may be associated with abnormal amino acid levels and changes in blood microenvironment, or may be related to the genetic variation of MMACHC and MTR C. 2756 and the subsequent decrease of MTR activity." (PMID 35495149, 2022).
methionine synthase deficiency (2 papers, 2013 to 2025). "Recently, a polymorphism in the methionine synthase (MTR) gene (2756A→G, rs1805087), resulting in the substitution of aspartic acid (D919) by glycine (G), was identified in patients with methionine synthase deficiency and was found to be polymorphic among healthy controls." (PMID 23613867, 2013).
Obesity (2 papers, 2012 to 2023). Accumulation of substantial excess body fat. "The results indicating a relationship between polymorphisms in the MTHFR and MTR genes and overweight/obesity are still controversial." (PMID 38203363, 2023). "Earlier reports have suggested variants from MTR to be associated with obesity, similar to this, we also observed variants of MTR (rs16834521) to be associated with BMI." (PMID 21960995, 2012). "Variants of MTHFR and other homocysteine metabolism pathway genes like MTR and MTRR have also been shown to be associated with obesity." (PMID 21960995, 2012). "A significant association was detected between genotypes AC of the MTHFR gene (OR = 2.5), AG of the MTR gene (OR = 3.0), and AG of the MTRR gene and the development of obesity." (PMID 38203363, 2023).
spina bifida (2 papers, 2009 to 2014). A congenital neural tube defect in which vertebrae are not fully formed. "For example, a SNP in the gene methionine synthase (MTR A2756G), in the enzyme required for folate-dependent remethylation of homocysteine, was initially shown to be significantly associated with increased risk for spina bifida in a candidate gene study." (PMID 25988111, 2014). "Blocks for TYMS, MTHFR, BHMT, and MTR showed some evidence of nonrandom effects for spina bifida." (PMID 19493349, 2009).
type 2 diabetes (2 papers, 2012 to 2020). "The specific molecular mechanisms of by which SCU improve type 2 diabetes model were to upregulate the key enzyme of Hcy metabolism MTHFR, MTR, CBS and CSE with their cofactor VitB12, VitB6 and folic acid." (PMID 33362535, 2020).
aneurysm (1 paper, 2021). Bulging or ballooning in an area of an artery secondary to arterial wall weakening. "A previous report indicated that polymorphisms in folate cycle enzymes, MTHFR, MTR, and MTRR, were related to aneurysm severity and dissection potential in MFS patients." (PMID 34769168, 2021).
aplastic anemia (1 paper, 2008). Anemia resulting from bone marrow failure (aplastic or hypoplastic bone marrow). "In fact, it has been reported that wild-type mice derived from the late generation of mTR+/− heterozygous parents which had short telomeres display hematopoietic phenotypes resembling aplastic anemia and dyskeratosis congenita." (PMID 18846223, 2008).
autoimmune disease (1 paper, 2023). A disorder resulting from loss of function or tissue destruction of an organ or multiple organs, arising from humoral or cellular immune responses of the individual to their own tissue constituents. "Previous studies have revealed the influence of various SNPs on the toxicity of MTX in patients with autoimmune diseases, such as MTHFR, MTR, ABCC1, ABCC2, and ABCG2." (PMID 37761008, 2023).
Azoospermia (1 paper, 2015). Absence of any measurable level of sperm,whereby spermatozoa cannot be observed even after centrifugation of the semen pellet. "In our meta-analysis, we found that MTR A2756G was associated with an increased risk of azoospermia and OAT.; however, when we removed the studies that did not conform to HWE, the overall ORs with their 95% CIs became meaningless." (PMID 26549413, 2015).
bone marrow failure (1 paper, 2009). "When crossed with mice deficient for the mouse TERC homologue mTR, POT1b−/− mTR+/− mice were generated that showed a significant reduction of telomere length, developed a severe and progressive bone marrow failure and died at around 4–5 months of age." (PMID 19419704, 2009).
colon cancer (1 paper, 2026). "Gene expression analysis of TCGA and GTEx identified the expression of the B12-dependent methionine synthase (MTR) to be elevated in colon cancer tissue, and increased MTR expression was associated with decreased colon cancer survival (65.8 months vs. undefined)." (PMID 41499753, 2026).
COVID-19 (1 paper, 2021). A disease caused by infection with severe acute respiratory syndrome coronavirus 2. "The most convincing evidence for association with severe COVID-19 was found for five loci: two folate metabolic genes (MTHFR and MTR), two hemostasis inhibitor genes (PROC and ADAMTS13), and a thrombospondin gene (THBS2)." (PMID 34834519, 2021).
dyslipidemia (1 paper, 2015). "In the present study, we investigated the association of folate, Hcy and several gene polymorphisms (MTHFR C677T, MTHFR A1298C, MTR A2756G and MTRR A66G) on serum lipid profiles and assessed the interactions of folate, Hcy and genotypes with dyslipidemia." (PMID 26337056, 2015). "In our study, MTR A2756G polymorphism independently not affects serum lipid profile or dyslipidemia." (PMID 26337056, 2015).
gestational diabetes (1 paper, 2023). Carbohydrate intolerance first diagnosed during pregnancy. "Elucidating the mechanism by which the organism favors TS activity over MTR activity is essential because many investigations have proposed elevated folate and reduced vitamin B12 interaction during gestational diabetes." (PMID 37799768, 2023).
glioblastoma multiforme (1 paper, 2011). "Though further studies are required to validate the suggested roles of MTR and CCNB1 in glioblastoma multiforme, our results demonstrate that CANGES is able to produce experimentally testable hypotheses that offer a solid ground for advanced analyses." (PMID 21533266, 2011).
gynecologic cancers (1 paper, 2023). "Analysis of the dataset of gynecologic cancers and controls revealed synergistic interactions between MTHFD1 rs2236225 and MTHFR rs1801133 (IG = 0.06%) and MTHFR rs1801133 and MTR rs1805087 (IG = 0.08%)." (PMID 37628752, 2023).
hepatoblastoma (1 paper, 2024). Hepatoblastoma (HB) is a malignant hepatic tumor and is the most common pediatric liver cancer. "One-carbon metabolism deregulation in hepatoblastoma tumors implicated 5-methyltetrahydrofolate-homocysteine methyltransferase (MTR), aldehyde dehydrogenase 1 family member L2 (ALDH1L2), and methylenetetrahydrofolate dehydrogenase (NADP+-dependent) 1-like (MTHFD1L)." (PMID 39684755, 2024).
Hyperglycemia (1 paper, 2011). An increased concentration of glucose in the blood. "Although they were lean, mTR+/− mice with short telomeres had fasting hyperglycemia compared with wild-type mice." (PMID 21423765, 2011).
hyperlipidemia (1 paper, 2015). "In hyperlipidemia patients, MTR 2756AG + GG carriers have higher total cholesterol and low-density lipoprotein cholesterol than those 2756AA carriers." (PMID 26337056, 2015).
hypothyroidism (1 paper, 2025). Abnormally low levels of thyroid hormone. "MTRR A66G and MTR A2756G polymorphisms are associated with hypothyroidism and metabolic comorbidities, both individually and in genotype combinations." (PMID 41150742, 2025). "This study examined associations between hypothyroidism and polymorphisms in MTHFR (C677T–rs1801133, A1298C–rs1801131), MTRR (A66G–rs1801394), and MTR (A2756G–rs1805087) genes." (PMID 41150742, 2025).
keloid (1 paper, 2025). An irregularly shaped, elevated mark on the skin caused by deposits of excessive amounts of collagen during wound healing. "Heat maps showed decreased expression of genes involved in Hcy catabolism, including CBS, MTR, 5-methylenetetrahydrofolate homocysteine methyltransferase reductase (MTRR), methylenetetrahydrofolate reductase (MTHFR), and methionine adenosyltransferase 1a (MAT1A) in keloids." (PMID 39919369, 2025).
liver dysfunction (1 paper, 2024). "To further elucidate the association between OCM and VPA-induced liver dysfunction, we analyzed the OCM pathway-related genetic variants (MTHFR A1298C, MTHFR C677T, MTR A2756G and MTRR A66G) in the ABLF and NLF groups." (PMID 38464726, 2024).
meningioma (1 paper, 2014). A generally slow growing tumor attached to the dura mater. "Several molecular epidemiological studies have been conducted to investigate the association of MTRR rs1801394 and MTR rs1805087 polymorphisms with meningioma." (PMID 24748989, 2014). "Therefore, we performed the present meta-analysis to investigate the association of the MTRR rs1801394 and MTR rs1805087 polymorphisms with susceptibility to meningioma." (PMID 24748989, 2014). "Therefore, we conducted the present meta-analysis to investigate the association of MTRR rs1801394 polymorphism with meningioma and provide updated information on the association of MTR rs1805087 polymorphism with meningioma." (PMID 24748989, 2014). "Several epidemiological studies suggested that methionine synthase (MTRR) rs1801394 and methionine synthase reductase (MTR) rs1805087 polymorphisms may be involved in the risk of meningioma in adults; however, the results from different case-control studies have been inconsistent." (PMID 24748989, 2014).
neutropenia (1 paper, 2025). A decrease in the number of neutrophils found in the blood. "The AA genotype (AA vs. G) of the MTR rs1805087 polymorphism was associated with concomitant neutropenia and thrombocytopenia (p = 0.01; OR = 2.69; 95% CI = 1.10–6.68)." (PMID 40430876, 2025).
ovarian tumor (1 paper, 2023). "In addition to the domains conservatively associated with viral replication, a 2OG-Fe(II) oxygenase superfamily (CDD accession cl21496) and an ovarian tumor (OTU) superfamily (CDD accession cl45892) were found in the intergenic region between MTR and HEL, with lower E-value of about 1e-10 to 1e-12." (PMID 38156006, 2023).
steatosis (1 paper, 2021). Increased lipid within the cytoplasm of cells. "Four genes had lower expression in steatosis (ABCA1, MTR, MTHFR, and PLG) and five genes had higher expression (SEPHS2, DIO1, HBB, SAA1, and SAA2) in the “selenoprotein micronutrient network” pathway." (PMID 34869521, 2021). "A total of two genes were common in two out of four datasets (MTR and GSTO1), but no gene was differentially expressed between HC and steatosis in all datasets." (PMID 34869521, 2021).